ZNF598 (zinc finger protein 598, E3 ubiquitin ligase)
Description:
E3 ubiquitin-protein ligase that plays a key role in the ribosome quality control (RQC), a pathway that takes place when a ribosome has stalled during translation, leading to degradation of nascent peptide chains. ZNF598 is activated when ribosomes are stalled within an mRNA following translation of prematurely polyadenylated mRNAs. Acts as a ribosome collision sensor: specifically recognizes and binds collided di-ribosome, which arises when a trailing ribosome encounters a slower leading ribosome, leading to terminally arrest translation. Following binding to colliding ribosomes, mediates monoubiquitination of 40S ribosomal proteins RPS10/eS10 and RPS3/uS3, and 'Lys-63'-linked polyubiquitination of RPS20/uS10. Polyubiquitination of RPS20/uS10 promotes recruitment of the RQT (ribosome quality control trigger) complex, which drives the disassembly of stalled ribosomes, followed by degradation of nascent peptides. E3 ubiquitin-protein ligase activity is dependent on the E2 ubiquitin-conjugating enzyme UBE2D3. Also acts as an adapter that recruits the 4EHP-GYF2 complex to mRNAs. Independently of its role in RQC, may also act as a negative regulator of interferon-stimulated gene (ISG) expression. (Microbial infection) Required for poxvirus protein synthesis by mediating ubiquitination of RPS10/eS10 and RPS20/uS10. Poxvirus encoding mRNAs contain unusual 5' poly(A) leaders and ZNF598 is required for their translational efficiency, possibly via its ability to suppress readthrough or sliding on shorter poly(A) tracts. (Microbial infection) Acts as a positive regulator of HIV-1 Tat stability independently of its E3 ubiquitin ligase activity, and reduces the 'Lys-48'-linked ubiquitination and prevents the proteasomal degradation of Tat. In turn, promotes HIV-1 replication and latent reactivation.
Synonyms: FLJ00086; HEL2
Gene: Protein-coding gene on chromosome 16 (1,997,654 to 2,009,821, reverse strand). Ensembl gene ENSG00000167962.
Subcellular location: Cytoplasm, cytosol
Subcellular location (Human Protein Atlas): Cytosol; Plasma membrane
Pathways (Reactome):
Metabolism of proteins: ZNF598 and the Ribosome-associated Quality Trigger (RQT) complex dissociate a ribosome stalled on a no-go mRNA
Genetic constraint (gnomAD): Loss-of-function variants: 48 observed, 62.01 expected, observed/expected ratio (o/e) 0.77, 90% interval 0.61 to 0.99. The synonymous counts are far from expectation, so gnomAD's model fits this gene poorly and the ratio says little. Missense variants: 1,311 observed, 1,079.2 expected, observed/expected ratio (o/e) 1.21, 90% interval 1.16 to 1.27. Synonymous variants: 701 observed, 473.86 expected, observed/expected ratio (o/e) 1.48, 90% interval 1.39 to 1.58.
Homologues: Orthologues: chimpanzee ZNF598 (98% identical), macaque ZNF598 (95% identical), mouse Zfp598 (82% identical), rat Zfp598 (81% identical), guinea pig ZNF598 (80% identical), pig ZNF598 (77% identical), dog ZNF598 (63% identical), tropical clawed frog znf598 (55% identical), zebrafish znf598 (50% identical), Drosophila melanogaster CG11414 (30% identical), Caenorhabditis elegans znf-598 (22% identical).
Diseases named in the same sentence as ZNF598 in open-access papers:
ZNF598 is named in the same sentence as 18 diseases in open-access papers, as found by Europe PMC text mining. Sharing a sentence is not in itself a finding about the gene and the disease. The quoted sentences say what the papers report.
viral infection (6 papers, 2020 to 2025). "Supporting a functional role of RQC in vaccinia viral infection, viral replication was impaired in cells deficient in ZNF598 activity or expressing a ubiquitination-deficient version of Rps20." (PMID 36187485, 2022). "Similar to the co-localization of GIGYF2 and Nsp2 near the DMVs, ZNF598 also co-localized with Nsp2 specifically upon viral infection." (PMID 40705924, 2025). "Oshiumi and colleagues found that ZNF598, which was known to dampen the induction of type I interferon-stimulated genes upon viral infection, attenuated the induction of type I interferons upon ZNF598 overexpression." (PMID 32586037, 2020). "Consistent with the idea of an increase in ribosome collisions during viral infection, it was shown that vaccinia virus infection leads to an increase in ubiquitination of the ribosomal protein uS10 by the ubiquitin ligase ZNF598, which is known to be directly activated by ribosome collisions." (PMID 37693516, 2023). "Crucially, it has previously been shown that ASCC3 or ZNF598 deficiency induces not only ISG expression but also a broad antiviral state: in the absence of these RQC factors, cells activate the inflammatory response to an extent that is sufficient to inhibit virus infection." (PMID 34111399, 2021). "Interestingly, recent studies indicate that ZNF598 and RACK1 may also suppress the innate immune response to viral infection via the RIG-I-MAVS signaling pathway, responsible for sensing cytosolic RNAs." (PMID 34111399, 2021). "Since ZNF598 and ASCC3 are both early RQC factors that sense ribosome collisions, future studies will test whether handling of ribosome collision is a common mechanism by which ZNF598 and ASCC3 negatively regulate ISG expression and antiviral response in various viral infection conditions." (PMID 36187485, 2022).
bladder cancer (1 paper, 2024). "The levels of RQC proteins ZNF598, NEMF, and ABCE1 induced by EME was decreased by co-treatment with CCCP in T24 and primary culture bladder cancer cells." (PMID 39315278, 2024).
brain tumor (1 paper, 2024). "In Notch-induced brain tumor condition, however, ZNF598 protein expression was up-regulated, and ZNF598 RNAi significantly reduced NB overgrowth, whereas ZNF598 OE showed slight enhancement." (PMID 39161732, 2024). "To examine the in vivo effect of ZNF598 on NSC homeostasis, we tested the effect of ZNF598 OE and RNAi under normal or in Notch-induced brain tumor conditions." (PMID 39161732, 2024).
glioblastoma (1 paper, 2024). The most malignant astrocytic tumor (WHO grade IV). "ZNF598 expression is up-regulated in human glioblastoma (GBM), and its expression positively correlates with that of cMyc." (PMID 39161732, 2024).
mesothelioma (1 paper, 2023). A usually malignant and aggressive neoplasm of the mesothelium which is often associated with exposure to asbestos. "In addition, ZNF598 expression was also decreased in most cancer types except mesothelioma (MESO)." (PMID 38140537, 2023).
osteosarcoma (1 paper, 2025). A usually aggressive malignant bone-forming mesenchymal neoplasm, predominantly affecting adolescents and young adults. "A recent study has shown that ZNF598 regulates cGAS activation in U2OS cells, the human osteosarcoma cell line via modulating ribosome collision and translation stress." (PMID 40337520, 2025).
renal carcinoma (1 paper, 2025). A carcinoma arising from the epithelium of the renal parenchyma or the renal pelvis. "MKRN2, ZNF598, UBE2D1, and TRIM25 were potential factors influencing renal cancer progression." (PMID 40959281, 2025).
cancer (8 papers, 2018 to 2026). A tumor composed of atypical neoplastic, often pleomorphic cells that invade other tissues. "Intriguingly, the SARS-COV-2-encoded translational regulator Nsp1 impinges on ZNF598 to restrain cMyc translation and consequently cMyc-dependent cancer growth." (PMID 39161732, 2024). "We find that ZNF598 expression is dependent on UV irradiation and its loss in different kind of cancer cells provides resistance to UV-induced apoptosis." (PMID 29464043, 2018). "Collectively, these analysis show that different cancer types have high frequency of mutations in ZNF598." (PMID 29464043, 2018). "Collectively, we demonstrate that loss of ZNF598 protects cancer cells from UV-induced apoptosis and is thus a new regulator of UV-induced apoptosis." (PMID 29464043, 2018). "Indeed, consistent with this model, Znf598 knockout RQC‐deficient cancer cells display higher sensitivity to 5‐Fluorouracil‐induced cell death." (PMID 38949989, 2025). "Therefore, we also asked if any alteration in ZNF598 such as copy-number loss/inactivating somatic mutations are observed in human cancer samples." (PMID 29464043, 2018). "Additionally, we find that loss of ZNF598 promotes cancer cell survival upon UV irradiation." (PMID 29464043, 2018). "Our results show that ribosome stalling during heightened cMyc translation and the up-regulated expression of translation factors such as ABCE1 by cMyc present vulnerabilities in cMyc-driven cancers that can be targeted by Nsp1 through the ZNF598 RQC pathway." (PMID 39161732, 2024). "Next, to measure the effect of UV irradiation on the expression of ZNF598, we irradiated multiple cancer cell lines with UV irradiation and measured ZNF598 mRNA level." (PMID 29464043, 2018). "To identify factors that protect cancer cells from UV-induced apoptosis, we performed a genome wide short-hairpin RNA (shRNA) screen, which identified Zinc finger protein 598 (ZNF598) as a key regulator of UV-induced apoptosis." (PMID 29464043, 2018). "We also find that when ZNF598 is knocked down in cancer cells, they become resistant to UV-induced apoptosis." (PMID 29464043, 2018). "The inhibition of ABCE1, ASCC3, and VCP has been shown to impede cancer cell proliferation and viability, while inhibiting NEMF/Clbn and ZNF598 may facilitate cancer cell growth and survival." (PMID 40785597, 2025). "Additionally, mitochondrial stress and treatment with the anti‐cancer chemotherapeutic drug 5‐Fluoruracil lead to post‐translational stabilization of ZNF598." (PMID 38949989, 2025). "We next sought to test the role of ZNF-598 in Myc-driven cancer growth." (PMID 39161732, 2024). "We found that UV irradiation leads to elevated expression of ZNF598 in multiple cancer cell lines." (PMID 29464043, 2018). "Lastly, in order to know whether inhibition of ELK1 has similar effect on the cells upon UV irradiation as ZNF598 knockdown, we UV irradiated variety of cancer cell lines expressing ELK1 shRNA to different UV doses and measured their survival ability." (PMID 29464043, 2018). "In our study, we find that cancer cells in response to UV irradiation upregulate ZNF598 expression." (PMID 29464043, 2018). "First, we find upon UV irradiation ZNF598 expression is up regulated in multiple cancer cell lines." (PMID 29464043, 2018). "Additionally, ZNF598 knockdown in cancer cells inhibited UV-induced apoptosis." (PMID 29464043, 2018). "To further investigate whether ZNF598 plays a role in UV-induced apoptosis, we used short-hairpin RNAs (shRNAs) to knock down its expression in a variety of human cancer cell lines of different tissue origin and analyzed the sensitivity of these cells to UV irradiation." (PMID 29464043, 2018). "Additionally, ZNF598 knockdown in cancer cells leads to resistance to UV-induced apoptosis." (PMID 29464043, 2018). "EME treatment led to increased levels of RQC proteins ZNF598 and ABCE1 at early time points in both T24 and primary cultured cancer cells." (PMID 39315278, 2024).
cancer (continued). "Further to test the role of ELK1 in regulating of ZNF598 level, we knocked down ELK1 expression using shRNAs in different types of cancer cell." (PMID 29464043, 2018). "However, 50 transcription factors displayed similar interactions with SWI/SNF in the two cancer types, such as several zinc-finger transcription factors (ZNF512, ZNF598, ZNF609, ZNF687, and ZNF709), CTCF, ELF2, and YBX1, indicating shared gene regulation networks." (PMID 40988026, 2025). "This was correlated with reduced cMyc and ZNF598 proteins levels and increased cMyc stalling as indicated by the increased S-cMyc/FL-cMyc ratio, and reduced cMyc target eIF4E level, supporting the relevance of the RQC of stalled cMyc translation in a mammalian cancer setting." (PMID 39161732, 2024). "Interestingly, RQC factors can display opposing functions in cancer development and suppression depending on specific circumstances, with some factors like ABCE1, ASCC3, and VCP suppressing cancer cell growth upon downregulation, while others like NEMF/Clbn and ZNF598 may promote it upon inhibition." (PMID 38798583, 2026).
tumor (4 papers, 2020 to 2025). "A significantly higher expression of ABCE1 and ZNF598 was found in tumor tissues compared to adjacent normal tissues." (PMID 39315278, 2024). "ZNF598 knockdown inhibits human GBM neurosphere formation in cell culture and Myc-dependent tumor growth in vivo in Drosophila." (PMID 39161732, 2024).
infection (2 papers, 2021 to 2025). The state of being infected such as from the introduction of a foreign agent such as serum, vaccine, antigenic substance or organism. "As observed in ZNF598 KO cells, overall host protein abundance was unchanged upon infection, but vaccinia virus protein production was broadly repressed in uS10-KI cells beginning 8 h post infection." (PMID 33912921, 2021). "To differentiate between these possibilities, we performed stable isotope labeling of amino acids in culture (SILAC)-based quantitative proteomics experiments upon infection with vaccinia virus in parental and ZNF598 KO cells." (PMID 33912921, 2021). "Direct comparison of early versus post-replicative viral protein abundance did not reveal any significant difference at any time point post infection in either ZNF598 KO or uS10-KI cells." (PMID 33912921, 2021). "An observable reduction in the mean vaccinia virus protein abundance in ZNF598 KO cells compared to parental controls could be detected 8 h post infection." (PMID 33912921, 2021). "Upon infection, GIGYF2 and ZNF598 relocate to areas near DMVs, viral replication sites." (PMID 40705924, 2025). "Heavy (Lys8)-labeled parental or ZNF598 KO cells were infected with vaccinia virus at a multiplicity of infection (MOI) of five, and cells were harvested at seven time points post infection then mixed with light (Lys0)-labeled uninfected cells of the same genotype." (PMID 33912921, 2021).
neurodegenerative disease (2 papers, 2020 to 2024). A disorder of the central nervous system characterized by gradual and progressive loss of neural tissue and neurologic function. "In Drosophila models of neurodegenerative diseases and patient cells, ZNF598 overexpression aborts stalled translation of mitochondrial outer membrane-associated mRNAs, removes faulty translation products causal of disease, and improves mitochondrial and tissue health." (PMID 38388640, 2024). "We hypothesize that this ZNF598 regulation by upstream stress signaling pathways may mechanistically link proteostasis, mitochondrial homeostasis, and innate immune response, failures of which constitute hallmarks of neurodegenerative diseases." (PMID 38388640, 2024). "Thus, by acting to minimise (via the GIGYF2 limb) and resolve (via the ZNF598 limb) ribosome collisions, both pathways seem to protect the proteome from detrimental translation products that may contribute to neurodegenerative disease." (PMID 32657267, 2020).
ZNF598 also shares sentences with these, for which no sentence is quoted: Alzheimer disease (1 paper); autism (1); breast carcinoma (1); colorectal cancer (1); COVID-19 (1); mild cognitive impairment (1); pancreatic cancer (1).